IGKV6-21 (immunoglobulin kappa variable 6-21 (non-functional))
Description:
V region of the variable domain of immunoglobulin light chains that participates in the antigen recognition. Immunoglobulins, also known as antibodies, are membrane-bound or secreted glycoproteins produced by B lymphocytes. In the recognition phase of humoral immunity, the membrane-bound immunoglobulins serve as receptors which, upon binding of a specific antigen, trigger the clonal expansion and differentiation of B lymphocytes into immunoglobulins-secreting plasma cells. Secreted immunoglobulins mediate the effector phase of humoral immunity, which results in the elimination of bound antigens. The antigen binding site is formed by the variable domain of one heavy chain, together with that of its associated light chain. Thus, each immunoglobulin has two antigen binding sites with remarkable affinity for a particular antigen. The variable domains are assembled by a process called V-(D)-J rearrangement and can then be subjected to somatic hypermutations which, after exposure to antigen and selection, allow affinity maturation for a particular antigen.
Synonyms: IGKV621; A26
Gene: Immunoglobulin variable (V) gene on chromosome 2 (89,159,751 to 89,160,366, reverse strand). Ensembl gene ENSG00000211611.
Subcellular location: Secreted; Cell membrane
Gene Ontology:
Biological process: immune response
Cellular component: extracellular region; immunoglobulin complex; plasma membrane
Homologues: Orthologues: mouse Igkv5-48 (67% identical), mouse Igkv5-43 (65% identical), mouse Igkv5-45 (65% identical), rat Igkv5-45l1 (65% identical), mouse Igkv5-39 (64% identical), mouse Igkv5-37 (61% identical). Paralogues in human: IGKV6D-21 (97% identical), IGKV6D-41 (75% identical), IGKV1D-12 (66% identical), IGKV1-12 (65% identical), IGKV1-39 (65% identical), IGKV1-9 (65% identical), IGKV1D-13 (65% identical), IGKV1D-39 (65% identical), IGKV1-8 (63% identical), IGKV1-27 (62% identical), IGKV1-6 (62% identical), IGKV1-17 (61% identical), and 81 more.